SNHG10 (small nucleolar RNA host gene 10)
Diseases named in the same sentence as SNHG10 in open-access papers (continued):
Sharing a sentence is not in itself a finding about the gene and the disease.
tumor (18 papers, 2020 to 2026). "Yet, in the context of CRC, the expression of lncRNA small nucleolar RNA host gene 10 (SNHG10) was upregulated in tumor tissues and associated with poor prognosis of CRC patients." (PMID 38571882, 2024). "Elevated expression of SNHG10, T stage, N stage, Gleason score, primary therapy outcome, residual tumor, and PSA were associated with PFS in patients with PCa." (PMID 37025585, 2023). "Moreover, SNHG10 expression was upregulated in tumor tissues in CRC, which was associated with poor prognosis." (PMID 34641864, 2021). "The depletion of SNHG10 in the PDAC xenograft model significantly reduced tumor growth, volume, and weight." (PMID 41916965, 2026). "Taken together, these data provided evidence for the tumor-suppressing role of the SNHG10/miR-200a-3p/BIN1 axis in EOC." (PMID 35149697, 2022). "In present study, we identified a novel tumor-suppressive lncRNA small nucleolar RNA host gene 10 (SNHG10) in EOC." (PMID 35149697, 2022). "For SigIQvar8, two genes (SNHG10 and RECQL4) are risk factors for ACC progression after adjusting for age at diagnosis and tumor stage." (PMID 35681785, 2022). "It was observed that SNHG10 was downregulated in TNBC tissues compared to that in non-tumor tissues (p < 0.0001)." (PMID 35506202, 2022). "Meanwhile, we knocked down SNHG10 expression to further confirm its tumor-suppressing effect in EOC cells." (PMID 35149697, 2022). "SNHG10 acted as a tumor-suppressor to inhibit tumorigenesis and EMT of EOC by regulating miR-200a-3p/BIN1." (PMID 35149697, 2022). "In summary, we demonstrated that the potential role of SNHG10 in regulating tumor progression and its potential application in the diagnosis and prognostic evaluation in PC." (PMID 34676212, 2021). "To compare the expression of SNHG10 in PC and normal samples, we analyzed the expression of SNHG10 in 499 tumor tissues and 52 normal prostate tissues of TCGA data, and found that SNHG10 was over-expressed in PC tissues (P < 0.001)." (PMID 34676212, 2021). "The results showed that DLEU2 and LINC00115 were markedly overexpressed in ccRCC samples compared with normal tissues, whereas the expression levels of COL18A1-AS1 and SNHG10 were remarkably lower in tumor tissues than those in the adjacent non-tumor samples." (PMID 34721523, 2021). "We observed the expression of SNHG10 was down-regulated in non-small cell lung cancer (NSCLC) compared with that in non-tumor tissues." (PMID 33081752, 2020). "Compared to non-tumor tissues, OS tissues exhibited significantly higher expression levels of SNHG10 (p < 0.001)." (PMID 32843060, 2020). "Sig27var25 and SigIQvar8 are highly effective at predicting ACC prognosis and progression; both signatures contain component genes predicting poor OS independently of age and tumor stages, for instance SNHG10 and RECQL4 for SigIQvar8 as well as MXD3, BIRC5, and RAB30 for Sig27var25." (PMID 35681785, 2022). "Moreover, overexpression of SNHG10 increased the sensitivity of TNBC cells to doxorubicin, suggesting that SNHG10 likely functions as a tumor suppressor in TNBC." (PMID 35506202, 2022). "The tumor weights of SNHG10 overexpression group were significantly reduced than the EV group." (PMID 35149697, 2022). "SNHG10 inhibition also decreased tumor cell colony formation." (PMID 34676212, 2021). "However, a recent report also argued SNHG10 as a tumor-repressor in non-small cell lung cancer (NSCLC)." (PMID 33298070, 2020). "In addition, SNHG10 regulates the expression of its homolog SCARNA13 to promote tumor metastasis." (PMID 35506202, 2022). "However, as compared to non-tumor tissues, the expression of SNHG10 in non-small cell lung cancer (NSCLC) is down-regulated, and its underlying mechanism could be the regulation of miR-21 gene methylation to enhance NSCLC cell proliferation." (PMID 35647035, 2022).
tumor (continued). "Silencing of SNHG10 decreases cell survival, proliferation, clonogenicity, EMT tumor growth through the EGFR/AKT/ERK/mTOR axis, and restores the expression of miR-150-5p, which eventually downregulates VEGF-A." (PMID 41916965, 2026). "Thus, SNHG10 might serve as a tumor-suppressing lncRNA in EOC by sponging miR-200a-3p." (PMID 35149697, 2022). "Altogether, SNHG10 sponges miR-200a-3p to upregulate BIN1 and thereby exerting its tumor-suppressive effects in EOC." (PMID 35149697, 2022). "We also measured the expression levels of SNHG10 in 60 sets of paired TNBC and adjacent non-tumor tissues from patients with TNBC and observed downregulation of SNHG10 in the TNBC tissues." (PMID 35506202, 2022). "Compared with non-tumor tissues, NSCLC tissues exhibited significantly lower expression levels of SNHG10 (p < 0.001)." (PMID 33081752, 2020). "The result showed that SNHG10 was downregulated in both LUAD (4.04 vs. 8.20) and LUSC (5.71 vs. 8.29) in comparison to that in tumor tissues." (PMID 33081752, 2020). "We confirmed this finding by determining the expression of SNHG10 in paired NSCLC and non-tumor tissues." (PMID 33081752, 2020). "In addition, we found that SNHG10 sponged miR-200a-3p to regulate the expression of bridging integrator-1 (BIN1), a tumor-suppressor downregulated in numerous cancers." (PMID 35149697, 2022). "In this study, we found SNHG10 was expressed at low levels in EOC tissues, indicating that SNHG10 might be a potential tumor-suppressing lncRNA." (PMID 35149697, 2022). "Moreover, we found that SNHG10 was highly expressed in CRC cells and overexpression of EMT exosomal SNHG10 significantly suppressed NK cell function, thereby contributing to tumor cell growth in vitro and in vivo." (PMID 34641864, 2021). "It was observed that the expression of SNHG10 and miR-218 were inversely and significantly correlated with each other across OS tissues, but not non-tumor tissues." (PMID 32843060, 2020). "Interestingly, SNHG10 and miR-302b were closely correlated across TNBC and non-tumor tissues, suggesting that they may interact with each other under both pathological and physiological conditions." (PMID 35506202, 2022). "Aiming at verifying the critical tumor-suppressing lncRNAs, we further analyzed the top 10 downregulated lncRNAs in EOC tissues of GSE135886 and GSE119054 datasets with R. The overlapped results showed that there were 5 common lncRNAs (SNHG10, TRHDE-AS1, linc00476, linc00893, NR2F2-AS1)." (PMID 35149697, 2022). "Moreover, the expression levels of miR-21 and SNHG10 were inversely and significantly correlated across NSCLC tissues, but not across non-tumor tissues evaluated by correlation analysis." (PMID 33081752, 2020).
cancer (11 papers, 2020 to 2026). A tumor composed of atypical neoplastic, often pleomorphic cells that invade other tissues. "Six NETs-related lncRNAs (AF131215.5, MYOSLID, NKILA, AC090152.1, SNHG10, and TRG.AS) have been reported to be associated with cancer progression." (PMID 34257164, 2021). "In this study, we investigated the role of SNHG10 in PC and found that SNHG10 expression was significantly increased in datasets extracted from The Cancer Genome Atlas." (PMID 34676212, 2021). "Small nucleolar RNA host gene 10 (SNHG10) has been reported to be a cancer-promoting gene in various human cancers." (PMID 34676212, 2021). "SNHG10 has been reported to function as an oncogene in multiple cancers, including GC." (PMID 36092901, 2022). "The effect of SNHG10 on tumorigenesis and progression varies in different cancers." (PMID 35149697, 2022). "The role of long non-coding RNA (lncRNA) small nucleolar RNA host gene 10 (SNHG10) has been investigated in many types of cancer, but its role in TNBC is unknown." (PMID 35506202, 2022). "TCGA database was used to identify the aberrant expression of SNHG10 across multiple cancers." (PMID 34676212, 2021). "Aberrant expression of SNHG10 has been elucidated in various human cancers." (PMID 34676212, 2021). "In addition, SNHG10 expression and patient survival was further investigated in various cancer types to expand our analysis to a pan-cancer level." (PMID 34676212, 2021). "The role of SNHG10 has been investigated in many types of cancer, but its role in TNBC is unknown." (PMID 35506202, 2022). "All these studies indicated that SNHG10 might exert a pivotal function in human cancers." (PMID 34676212, 2021). "Therefore, SNHG10 and miR-218 may serve as potential targets for OS treatment by regulating cancer glucose uptake." (PMID 32843060, 2020). "Small nucleolar RNA host gene 10 (SNHG10) has emerged as a key regulator in the progression and metastasis of human cancers." (PMID 41916965, 2026). "Therefore, SNHG10 may play different roles in different types of cancer." (PMID 35506202, 2022). "As novel drivers of the malignant phenotype of HCC, SNHG10 and its homolog SCARNA13, which form a positive feedback loop, coordinately contribute to the cancer development." (PMID 34257164, 2021). "However, the role of SNHG10 in other cancers remains unclear." (PMID 32843060, 2020). "SNHG10 predicts the prognosis of NSCLC, and it can downregulate miR-21 through methylation to suppress the proliferation of cancer cells." (PMID 33081752, 2020). "The expression of SNHG10 was also higher in cancer samples than matched adjacent normal samples (P < 0.01)." (PMID 34676212, 2021).
SNHG10 also shares sentences with these, for which no sentence is quoted: acute myeloid leukemia (2 papers); asthma (1); head and neck squamous cell carcinoma (1); hepatoblastoma (1); liver fibrosis (1); pancreatic ductal adenocarcinoma (1); thymoma (1); triple-negative breast carcinoma (1).